MSTN (myostatin)
Diseases named in the same sentence as MSTN in open-access papers (continued):
Sharing a sentence is not in itself a finding about the gene and the disease.
asthma (3 papers, 2021 to 2024). "To date, at least two of the most common lung tissue diseases associated with MSTN expression have been identified, namely, COPD and asthma." (PMID 38473184, 2024). "In the first stage, horses with severe asthma were selected, and in the second stage, the myostatin level was determined in horses classified as asthmatic or healthy (controls)." (PMID 38473184, 2024). "Recent studies provide evidence for the usefulness of one myokine in the diagnosis of human asthma, namely, myostatin." (PMID 38473184, 2024). "Numerous studies have found elevated plasma concentrations of one of the myokines, namely, myostatin (MSTN), in people suffering from severe asthma." (PMID 38473184, 2024). "Probably, a different breed, age, and type of physical activity are factors that affect plasma myostatin levels to a great extent than the presence of asthma in horses." (PMID 38473184, 2024). "Our finding that higher myostatin levels are associated with poorer response to mepolizumab might imply that these patients met criteria for eosinophilic asthma based on their peripheral eosinophil counts but that the underlying mechanism driving their asthma is neutrophilic or mixed granulocytic." (PMID 38057814, 2023). "Given the pathogenesis of asthma, MSTN could be also a useful biomarker of asthma in horses; however, the skeletal muscle mass and/or training status could also be factors influencing plasma MSTN concentration in horses." (PMID 38473184, 2024). "A possible reason for differences in MSTN concentration in humans with asthma and horses with severe equine asthma could be related to the role of MSTN in muscle metabolism and the distinct physiological responses to chronic respiratory conditions in each species." (PMID 38473184, 2024). "Therefore, given the pathogenesis of asthma, we hypothesize that MSTN could be a useful biomarker of equine asthma." (PMID 38473184, 2024). "We hypothesized that the level of MSTN in horses affected by asthma should be high, due to the presence of local hypoxia in airway smooth muscle (ASM); hence, we investigated whether MSTN could be a useful marker of EA." (PMID 38473184, 2024).
cor pulmonale (3 papers, 2016 to 2024). Hypertrophy and dilation of the right ventricle of the heart that is caused by pulmonary hypertension. "As COPD primarily affects the right side of the heart and leads to cor pulmonale, it was supposed that myostatin levels might be associated with RV dysfunction in cor pulmonale in COPD." (PMID 26998756, 2016). "In summary, the present study has shown that plasma myostatin levels are remarkably increased in COPD patients who had cor pulmonale and correlated with RV function and geometry in advanced COPD." (PMID 26998756, 2016). "Plasma myostatin levels are increased in COPD patients who have cor pulmonale." (PMID 26998756, 2016). "Stronger correlations of plasma myostatin levels with echocardiographic indexes of the right heart suggest that myostatin might be superior to BNP in the early diagnosis of cor pulmonale in COPD." (PMID 26998756, 2016). "One of the key findings in the present study was that myostatin levels increased remarkably in the 39 patients with COPD who had cor pulmonale compared with controls, and the levels were also significantly higher compared with patients who did not have cor pulmonale." (PMID 26998756, 2016). "Furthermore, these limitations did not interfere with the finding that plasma levels of myostatin were higher in patients with cor pulmonale and associated with the severity of the RV dysfunction in advanced COPD." (PMID 26998756, 2016). "Therefore, this study indicates that, in comparison with BNP, myostatin might be a stronger indicator for cor pulmonale in advanced COPD." (PMID 26998756, 2016). "First, plasma myostatin levels were higher in patients with COPD and much higher in those who had cor pulmonale, when compared with controls." (PMID 26998756, 2016). "Plasma BNP levels, which were analyzed in the present study in comparison with myostatin, were also higher in COPD patients compared with controls, and much higher in those who had cor pulmonale." (PMID 26998756, 2016). "Plasma myostatin levels were higher in the COPD patients than in controls, especially in those with cor pulmonale." (PMID 26998756, 2016). "Plasma myostatin levels (ng/mL) were significantly higher in patients with cor pulmonale (16.68 ± 2.95) than in those without (13.56 ± 3.09), and much higher than in controls (8.79±2.79), with each p<0.01." (PMID 26998756, 2016). "Thus, it was not very clear whether cardiac myostatin levels were elevated in patients with cor pulmonale." (PMID 26998756, 2016).
dermatomyositis (3 papers, 2021 to 2023). Dermatomyositis (DM) is a type of idiopathic inflammatory myopathy characterized by evocative skin lesions and symmetrical proximal muscle weakness. "We found out that myostatin expression is decreased and correlates with disease activity, thus rising up when patients' disease activity is controlled, particularly in dermatomyositis and antisynthetase syndrome patients." (PMID 36168256, 2023). "Some human diseases with enhanced myostatin plasma levels including dermatomyositis and CKD are characterized by enhanced FGF23 production." (PMID 33895875, 2021). "In dermatomyositis, an inflammatory condition, the plasma myostatin concentration is elevated." (PMID 33895875, 2021). "Prospective assessment of myostatin protein level in 447 IIM serum samples (dermatomyositis [DM], n = 157; IBM, n = 72; IMNM, n = 125; and antisynthetase syndrome [ASyS], n = 93) and 59 healthy donors (HD) was performed by ELISA." (PMID 36168256, 2023).
dystrophin deficiency (3 papers, 2015 to 2022). "Our data support the observation that the two dystrophinopathy patients who presented advanced muscle atrophy are the only cases showing reduced myostatin levels, that correlated with their reduced muscle mass." (PMID 32961888, 2020).
endothelial dysfunction (3 papers, 2024 to 2025). In vascular diseases, endothelial dysfunction is a systemic pathological state of the endothelium (the inner lining of blood vessels) and can be broadly defined as an imbalance between vasodilating and vasoconstricting substances produced by (or acting on) the endothelium. "The positive association between myostatin and endothelial dysfunction in CKD highlighted the mechanisms of CKD-associated vasculopathy." (PMID 39727658, 2024). "Our study found an inverse association between serum myostatin and eGFR, which may contribute to impaired renal clearance, enhanced inflammation status, and endothelial dysfunction in advanced CKD." (PMID 39727658, 2024). "Finally, given the cross-sectional design of our study, our findings should be regarded as hypothesis-generating, and causal relationships between myostatin levels and endothelial dysfunction cannot be established." (PMID 39727658, 2024). "Previous research has demonstrated that worsening endothelial dysfunction with eGFR deterioration and increased myostatin levels in early atherosclerotic lesions contributed to uremic vasculopathy." (PMID 39727658, 2024). "We hypothesized that myostatin and indoxyl sulfate may synergistically induce endothelial dysfunction by impairing endothelial proliferation and promoting a pro-inflammatory phenotype." (PMID 40278657, 2025). "While our study focused on traditional lipid markers, incorporating apolipoproteins in future research could enhance the characterization of cardiovascular risk and deepen our understanding of the interplay between lipid metabolism, myostatin levels, and endothelial dysfunction in CKD populations." (PMID 39727658, 2024). "Specifically, the potential of circulating myostatin to serve as a standalone indicator of endothelial dysfunction in CKD patients who are not on dialysis has yet to be fully established." (PMID 39727658, 2024). "Our study suggests that serum myostatin may serve as an independent predictor of endothelial dysfunction in non-dialysis CKD stages 3–5." (PMID 39727658, 2024).
Huntington disease (3 papers, 2015 to 2021). Huntington disease (HD) is a rare neurodegenerative disorder of the central nervous system characterized by unwanted choreatic movements, behavioral and psychiatric disturbances and dementia. "Also, activin A protects from neural degeneration in individuals with Huntington’s disease, and the relationship between myostatin and activin has been well established." (PMID 25710176, 2015).
myositis (3 papers, 2020 to 2023). "Further prospective studies are needed to validate the usefulness of myostatin in the follow‐up of myositis patients." (PMID 36168256, 2023). "The level of myostatin was also assessed in each of the four myositis subgroups and again compared to HD (ASyS n = 93, DM n = 157, IMNM n = 125 and IBM n = 72)." (PMID 36168256, 2023). "This investigation’s finding of higher MSTN levels in DM patients compared to controls is in contrast to one study evaluating different myositis subtypes." (PMID 33546660, 2021).
myotubular myopathy (3 papers, 2017 to 2022). "We also provide in vivo evidence in the congenital myotubular myopathy mouse model (knock-out for the myotubularin coding gene Mtm1) that a down-regulated myostatin pathway can be reactivated by correcting the underlying gene defect." (PMID 29192144, 2017).
Parkinson disease (3 papers, 2015 to 2026). A progressive degenerative disorder of the central nervous system characterized by loss of dopamine producing neurons in the substantia nigra and the presence of Lewy bodies in the substantia nigra and locus coeruleus. "The resultant analysis revealed myostatin overexpression in the gastrocnemius muscle following the induction of chronic parkinsonism by MPTP/p treatment." (PMID 35400955, 2022).
peripheral artery disease (3 papers, 2021 to 2023). "The treatment with myostatin-targeting ARC significantly silenced myostatin expression and hypertrophy of the gastrocnemius muscle after intramuscular injection in a mouse model of peripheral artery disease." (PMID 36770585, 2023).
pulmonary disease (3 papers, 2013 to 2024). "Induction of myostatin expression was observed in rodent models of muscle wasting and in cachectic patients with cancer or pulmonary disease." (PMID 24260393, 2013). "In contrast to the cancer patients, patients with pulmonary disease and chronic cachexia/underweight showed a dramatic increase in the serum levels of myostatin prodomain." (PMID 24260393, 2013).
anemia (2 papers, 2021 to 2025). A reduction in the number of red blood cells, the amount of hemoglobin, and/or the volume of packed red blood cells. "LDN193189 also shows promise in other therapeutic areas through its promotion of myoblast differentiation by inhibiting GDF8/myostatin signaling29and its attenuation of inflammation-associated anemia by reducing hepcidin expression." (PMID 40287480, 2025). "Counteraction of ACVR2B ligands was able to reverse anemia in C26 hosts independent of the administration protocol and in inhibin-deficient mice, while ApcMin/+ mice presenting myostatin gene inactivation were also free from anemia." (PMID 33671024, 2021).
anorexia nervosa (2 papers, 2020 to 2022). A disorder most often seen in adolescent females characterized by a refusal to maintain a minimally normal body weight, an intense fear of gaining weight, a disturbance in body image, and, in postmenarcheal females, the development of amenorrhea. "Age-related declines in aBMD were reported to be attenuated in myostatin-deficient mice, although, conversely, no direct link was observed between circulating myostatin levels and aBMD in various human populations like postmenopausal and elderly women or young women with anorexia nervosa." (PMID 32316563, 2020).
arteriosclerosis (2 papers, 2013 to 2024). A vascular disorder characterized by thickening and hardening of the walls of the arteries.
breast tumor (2 papers, 2015 to 2023). "Since myostatin promotes apoptosis in breast tumor cells, the overexpression of Titin-Cap would be expected to strongly promote breast tumor proliferation." (PMID 26543765, 2015).
Cerebral ischemia (2 papers, 2017 to 2022). Restriction of arterial blood supply to the brain associated with insufficient oxygenation to support the metabolic requirements of the tissue. "A common complication of cerebral ischemia is loss of skeleton and muscle mass, which is associated with myostatin." (PMID 35395053, 2022). "We therefore tested the hypothesis that myostatin inhibition would improve recovery of skeletal muscle mass and function after cerebral ischemia." (PMID 29070788, 2017). "Therefore, we hypothesized that inhibition of myostatin would improve skeletal muscle mass and function after cerebral ischemia." (PMID 29070788, 2017).
Cognitive impairment (2 papers, 2024 to 2026). Abnormal cognition is characterized by deficits in thinking, reasoning, or remembering. "Two additional proteins (myostatin and integrin aVb5) were instead related to lower chances of baseline cognitive impairment or dementia." (PMID 38337499, 2024). "Likewise, plasma concentrations of myostatin, PI3, TFF3, and PAPPA have been shown to identify at-risk individuals with high accuracy and well before clinical signs of cognitive impairment appear." (PMID 38337499, 2024).
colon carcinoma (2 papers, 2017). "We further investigated alternative mechanisms underlying FoxO3 modulation and asked whether the Akt/FoxO3 and myostatin/Smad3 axis were affected by implanted C26 colon carcinoma cells and JQ1 administration." (PMID 29167426, 2017). "In conclusion, we demonstrated that co-culture of C2C12 myotubes with CT26 colon carcinoma cells increased TNF-α and myostatin concentrations in the culture medium." (PMID 29069832, 2017). "In this study, co-culture of C2C12 myotubes with CT26 colon carcinoma cells increased TNF-α and myostatin concentrations in the medium and altered the metabolism of C2C12 myotubes, indicating that these two types of cells interact with each other via secreted factors." (PMID 29069832, 2017).
congenital heart disease (2 papers, 2011 to 2021). A heart disease that is present at birth. "Increased myocardial expression of myostatin was noted in congenital heart disease, and an increase in the ratio of myostatin to insulin-like growth factor 1 correlated with worsening of LV function." (PMID 34479416, 2021). "To date, the regulation of myostatin in congenital heart disease (CHD) has not been described." (PMID 21931616, 2011).
diabetic nephropathy (2 papers, 2020 to 2023). "In diabetic nephropathy patients, the expression level of MSTN in renal tubules is increased, and MSTN induced the release of ROS and up-regulation of NADPH oxidase in cells through the ERK pathway, thus aggravate the progression of tubule cell fibrosis." (PMID 37288303, 2023). "In this study we observed upregulation of MSTN mRNA (~8 to 10-fold increase) both in the glomeruli and tubulointerstitium in diabetic nephropathy (DN)." (PMID 32286342, 2020).
dysferlinopathy (2 papers, 2015 to 2024). "Here, we show that inhibition of myostatin signaling indeed can result in an exacerbation of muscle degeneration in the setting of dysferlinopathy." (PMID 26206886, 2015). "To investigate the effect of blocking myostatin signaling in the setting of dysferlinopathy, we used both genetic and pharmacological approaches in mice." (PMID 26206886, 2015).
infertile (2 papers, 2022). "Any dysregulation or change in MSTN or its receptors may impact related intracellular pathways and influence ovarian functions, accounting for various reproductive diseases, including infertility." (PMID 35780124, 2022).
Lewis Lung carcinoma (2 papers, 2015 to 2016). "In fact, inactivation of myostatin by treatment with a soluble form of activin receptor IIB (sACTRIIB) ablated the symptoms of cancer cachexia in mice bearing Lewis lung carcinoma." (PMID 26668061, 2015). "In a previous study, wild type mice and mice bearing the Lewis Lung carcinoma showed hyperphosphorylation of p38 MAPK as well as inhibition of AKT signaling and activation of the myostatin pathway in response to different chemotherapeutics." (PMID 27259276, 2016).
lipid metabolic disorders (2 papers, 2021 to 2026). "Second, we found that SARS-CoV-2 infection could modulate the expression of MPO, apelin, and myostatin by up-regulating transcription factor REST, which may lead to glucose and lipid metabolic disorders." (PMID 34916489, 2021).
nemaline myopathy (2 papers, 2018 to 2023). Nemaline myopathy (NM) encompasses a large spectrum of myopathies characterized by hypotonia, weakness and depressed or absent deep tendon reflexes, with pathologic evidence of nemaline bodies (rods) on muscle biopsy. "Collectively, these findings indicate that inhibiting myostatin can mitigate the muscle deficits in nebulin-based typical nemaline myopathy, potentially serving as a much-needed therapeutic option." (PMID 37894805, 2023).
Osteopenia (2 papers, 2024 to 2025). Osteopenia is a term to define bone density that is not normal but also not as low as osteoporosis. "Targeting myostatin pathways in the gestational environment provides a potential therapeutic approach for inherited osteopenia." (PMID 39066929, 2024).
pancreatitis (2 papers, 2023 to 2025). Inflammation of the pancreas. "Additionally, serum concentrations of anabolic (oxytocin) and catabolic (myostatin) mediators exhibited alterations typical of muscle atrophy; oxytocin levels were markedly reduced, whereas myostatin levels were markedly elevated from the third week post-induction of pancreatitis until euthanasia." (PMID 40869011, 2025).
renal fibrosis (2 papers, 2020 to 2025). A final common manifestation of a wide variety of chronic kidney diseases characterized by glomerulosclerosis and tubulointerstitial fibrosis. "Interestingly, while inhibiting MSTN has been implicated in improving fibrosis in skeletal muscle, its inhibition in this context did not reduce renal fibrosis." (PMID 40243849, 2025). "In our model, we observed a MSTN-induced increase in the expression of ERK and P-38 MAPK phosphorylation that may promote the development of renal fibrosis through the SMAD-independent pathway." (PMID 32286342, 2020).
rotator cuff tear (2 papers, 2018 to 2024). "To date, only a few genes, such as those coding for peroxisome proliferator-activated receptors gamma (PPARγ), CCAAT-enhancer-binding proteins alpha (CEBPα), myogenin, myostatin, and matrix metallopeptidases (MMPs), have been identified in relation to muscle changes after rotator cuff tears." (PMID 30671462, 2018).